FUT9 (fucosyltransferase 9)
Description:
Catalyzes alpha(1->3) linkage of fucosyl moiety transferred from GDP-beta-L-fucose to N-acetyl glucosamine (GlcNAc) within type 2 lactosamine (LacNAc, beta-D-Gal-(1->4)-beta-D-GlcNAc-) glycan attached to glycolipids and N- or O-linked glycoproteins. Fucosylates distal type 2 LacNAc and its fucosylated (H-type 2 LacNAc) and sialylated (sialyl-type 2 LacNAc) derivatives to form Lewis x (Lex) (CD15) and Lewis y (Ley) antigenic epitopes involved in cell adhesion and differentiation. Generates Lex epitopes in the brain, presumably playing a role in the maintenance of neuronal stemness and neurite outgrowth in progenitor neural cells (By similarity). Fucosylates the internal type 2 LacNAc unit of the polylactosamine chain to form VIM-2 antigen that serves as recognition epitope for SELE. Can also modify milk oligosaccharides, in particular type 2 tetrasaccharide LNnT.
Synonyms: Fuc-TIX
Tractability: Small molecule: a structure with a bound ligand is known. Antibody: UniProt predicts a signal peptide or a membrane-spanning region.
Target class: Enzyme; Transferase
Gene: Protein-coding gene on chromosome 6 (96,015,436 to 96,215,612, forward strand). Ensembl gene ENSG00000172461.
Subcellular location: Golgi apparatus, trans-Golgi network membrane; Golgi apparatus membrane
Subcellular location (Human Protein Atlas): Nucleoplasm; Cytokinetic bridge; Cytosol; Microtubules
Pathways (Reactome):
Metabolism: Lewis blood group biosynthesis
Gene Ontology:
Molecular function: 4-galactosyl-N-acetylglucosaminide 3-alpha-L-fucosyltransferase activity; alpha-(1->3)-fucosyltransferase activity; protein binding; protein homodimerization activity; fucosyltransferase activity
Biological process: glycosphingolipid biosynthetic process; Lewis x epitope biosynthetic process; N-glycan processing; neuron differentiation; oligosaccharide biosynthetic process; positive regulation of neuron projection development; protein N-linked glycosylation; protein O-linked glycosylation; regulation of leukocyte cell-cell adhesion; regulation of leukocyte tethering or rolling; carbohydrate metabolic process; glycoprotein biosynthetic process; L-fucose catabolic process; polysaccharide biosynthetic process; neuronal stem cell division; sphingolipid metabolic process
Cellular component: trans-Golgi network; trans-Golgi network membrane; Golgi apparatus; Golgi membrane; membrane
Genetic constraint (gnomAD): Loss-of-function variants: 13 observed, 27.05 expected, observed/expected ratio (o/e) 0.48, 90% interval 0.31 to 0.76. The upper end of that interval is the gene's LOEUF score, 0.76, which puts it in group 3 of 6, group 1 being the genes least tolerant of losing a copy. Missense variants: 291 observed, 409.92 expected, observed/expected ratio (o/e) 0.71, 90% interval 0.64 to 0.78. Synonymous variants: 157 observed, 150.7 expected, observed/expected ratio (o/e) 1.04, 90% interval 0.91 to 1.19.
Homologues: Orthologues: chimpanzee FUT9 (100% identical), macaque FUT9 (100% identical), rabbit FUT9 (99% identical), dog FUT9 (99% identical), mouse Fut9 (99% identical), pig FUT9 (99% identical), guinea pig FUT9 (99% identical), rat Fut9 (99% identical), tropical clawed frog fut9 (83% identical), zebrafish fut9a (59% identical), zebrafish FUT9 (48% identical), zebrafish ft1 (47% identical), and 16 more. Paralogues in human: FUT4 (39% identical), FUT5 (37% identical), FUT3 (37% identical), FUT6 (36% identical), FUT7 (36% identical), POFUT3 (24% identical), POFUT4 (23% identical).
Diseases named in the same sentence as FUT9 in open-access papers:
FUT9 is named in the same sentence as 30 diseases in open-access papers, as found by Europe PMC text mining. Sharing a sentence is not in itself a finding about the gene and the disease. The quoted sentences say what the papers report.
colon cancer (6 papers, 2017 to 2025). "FUT9 has been associated with colon cancer progression both by induction of cell dedifferentiation into a stem-like state, and by metabolic remodeling." (PMID 35625673, 2022). "FUT9 gene encoding the α-1,3 fucosyltransferase, plays a complex dual role in colon cancer development and malignancy." (PMID 35936672, 2022). "Here, we show that FUT9 expression is associated with resistance to chemotherapeutic drugs both in murine and human colon cancer cells." (PMID 32927726, 2020). "To gain more insight into the pathways associated with high FUT9 expression in human colon cancer cells, we performed a gene ontology analysis in the ‘FUT9-High’ cluster using the R2 genomics analysis and visualization platform." (PMID 32927726, 2020). "These predictions imply that the loss of FUT9, while hampering the growth of adenomas, is required for the proliferation of colon tumors, while its overexpression significantly reduces proliferation in that state." (PMID 29196508, 2017). "Thus, FUT9 expression in human colon cancer cells is linked both to stemness signaling and an early-driving event (IBD) of this disease." (PMID 32927726, 2020). "Furthermore, we observed a vigorous association between FUT9 expression and the Notch and Hedgehog signaling pathways in human primary colon cancer cells and cell lines." (PMID 32927726, 2020). "We find that the expression of metabolic genes associated with reactions predicted to increase following FUT9 loss is significantly upregulated in stage 4 vs. stage 3 colon tumors when compared by their expression in TCGA data (hyper‐geometric P‐value = 0.0046, Table EV6)." (PMID 29196508, 2017). "FUT9 is known to dictate stemness in embryonic and neuronal cells and it has been proposed to act as a metabolic driver of advanced-stage colon cancer." (PMID 32927726, 2020). "Nevertheless, the impact of FUT9 expression on stemness acquisition by colon cancer cells, along with other functional features of CSCs such as drug resistance, remains ill defined." (PMID 32927726, 2020). "So, going forward, the impact of FUT9 expression on resistance acquired by colon cancer cells to other types of therapy remains to be evaluated." (PMID 32927726, 2020). "Our data demonstrate that, besides cMyc, FUT9 expression is correlated with Sox2 expression both in murine and human colon cancer cells." (PMID 32927726, 2020). "Our results provide evidence that FUT9 dictates a stem cell-like fate in colon cancer cells both in mice and humans, suggesting a conserved role of this enzyme during malignant transformation and tumor fueling." (PMID 32927726, 2020). "Here, we explored the major regulatory programs instructed in colon cancer cells upon FUT9 expression by combining computational and experimental analyses." (PMID 32927726, 2020). "Our paper outlines the role of aberrant fucosylation by the Fucosyltransferase 9 (FUT9) as a potent reprogramming factor marking the acquisition of a stem-like state both by murine and human colon cancer cells." (PMID 32927726, 2020). "Conclusively, FUT9 expression in the MC38 colon cancer model led to induction of a stemness-oriented ‘cis-meta-regulon’, a CSC-like transcriptional profile and key phenotypic and functional characteristics of tumor-initiating cells." (PMID 32927726, 2020). "In summary, our work suggests FUT9 as a potent reprogramming factor marking the acquisition of a stem-like and drug resistance phenotype by murine and human colon cancer cells." (PMID 32927726, 2020). "Our results provide evidence that FUT9 is responsible for the hardwiring of both murine and human colon cancer cells towards a CSC-like transcriptional profile, phenotype and function, with major implications for tumor growth and resistance to chemotherapy." (PMID 32927726, 2020).
colon cancer (continued). "To confirm the direct involvement of FUT9 in the CSC-like phenotype of human colon cancer cell lines, we proceeded with CRISPR-Cas9-mediated knock-out (KO) of FUT9 in the top two FUT9-High cell lines, KM12 (CMS1 subtype) and SW1116 (CMS2 subtype) cells." (PMID 32927726, 2020). "Taken together, we reverse-engineered the transcriptional regulatory network of MC38-glycovariants via iRegulon and exploited it to elucidate which molecular programs are instructed by FUT9 in colon cancer cells." (PMID 32927726, 2020). "We present a novel approach for identifying metabolic tumor suppressors that leads to the discovery of the complex, multi‐faceted role of FUT9 in colon cancer." (PMID 29196508, 2017). "Experimental testing reveals FUT9's complex dual role; while its knockdown enhances proliferation and migration in monolayers, it suppresses colon cancer cells expansion in tumorspheres and inhibits tumor development in a mouse xenograft models." (PMID 29196508, 2017). "To test the prediction that FUT9 downregulation supports colon cancer aggressiveness, we silenced its expression using shRNA‐based knockdowns in two colorectal cancer cell lines, HCT116 and DLD1 that express FUT9." (PMID 29196508, 2017). "Our analysis predicts FUT9, which catalyzes the biosynthesis of Ley glycolipids, as a driver of advanced‐stage colon cancer." (PMID 29196508, 2017). "Therefore, in order to unravel the full range of molecular programming instructed by FUT9 expression in the context of colon cancer, we proceeded with transcriptional induction of the Fut9 gene in MC38-WT cells using the CRISPR-dCas9-VPR system." (PMID 32927726, 2020). "Similarly, we found the beta‐1,3‐N‐acetylglucosaminyltransferase B3GNT8 to be upregulated (fold change = 3.46), in FUT9 knockdown cells, consistent with previous reports in colon cancer." (PMID 29196508, 2017). "However, the knockdown of FUT9 promoted proliferation and migration in monolayers but inhibited the stemness of colon cancer cells, which might be because the inhibition of FUT9 attenuates tumor-initiating cells (TICs) but promotes bulk tumor cells." (PMID 40821120, 2025). "Hence, we set out to assess the role of FUT9 in colon cancer stemness induction." (PMID 32927726, 2020). "Our genomic analysis revealed that, while FUT9 is strongly downregulated at later stages of colon cancer development, it is still present in colon polyps and early adenoma, indicating that FUT9 activity may be required at the initial stages of tumor initiation." (PMID 29196508, 2017). "Our subsequent experimental study of FUT9 function indicates that it plays a more complex, dual role in this malignancy; its expression in TICs favors tumor initiation, while subsequent colorectal cancer progression via the mass of colon cancer bulk tumors is supported by its downregulation." (PMID 29196508, 2017). "Taken together, these findings are consistent with the CSC-like phenotype and function of MC38-FUT9 cells, hinting to a positive correlation between FUT9 expression and CSC-like features in human colon cancer cells as well." (PMID 32927726, 2020). "Given that ALDH marks pluripotency both in healthy and cancer cells, these results suggest indispensable involvement of FUT9 in reprogramming of human colon cancer cell lines towards a stem-like phenotype, a process that seems to be FUT9-specific, but not necessarily Lewisx-dependent." (PMID 32927726, 2020).
colon adenocarcinoma (2 papers, 2020 to 2023). "De novo transcriptional activation of Fut9 in the murine colon adenocarcinoma cell line, MC38, followed by RNA seq-based regulon analysis, revealed major gene regulatory networks related to stemness." (PMID 32927726, 2020). "Here, we followed this approach to detect the regulatory circuits of hub genes and TFs that are in play upon transcriptional activation of Fut9 in the murine colon adenocarcinoma cell line, MC38." (PMID 32927726, 2020). "Moreover, highly expressed FUT9 was responsible for preventing murine colon adenocarcinoma MC38 cells bearing stem-like phenotypes from 5-FU-induced cell death." (PMID 37298124, 2023).
colorectal cancer (2 papers, 2017 to 2019). A primary or metastatic malignant neoplasm that affects the colon or rectum. "We found that the loss of FUT9 in late‐stage colorectal cancers is predicted to cause an increase in the flux of 25 reactions, and a decrease in the flux of six reactions (Table EV6)." (PMID 29196508, 2017). "However, it is still unknown whether increased expression of FUT4 and FUT9, influencing the abundance of α2-3-linked sialic acids on N-glycans, is associated with decreased Siglec binding to colorectal cancer cells and modulation of the anti-tumor immune response in vivo." (PMID 30476078, 2019). "In the present study, we exploited the CRISPR-dCas9-VPR system for transcriptional activation of certain α1-3 fucosyltransferase genes, Fut4 and Fut9, playing a major role in colorectal cancer pathogenesis." (PMID 30476078, 2019). "In agreement, we find that FUT9 silencing decreases the expression of the colorectal cancer TIC marker CD44 and the level of the OCT4 transcription factor, which is known to support cancer stemness." (PMID 29196508, 2017). "Reduced FUT9 expression at the M1 metastatic stage also matches our observations, suggesting that FUT9 downregulation enhances migration of colorectal cancer cells." (PMID 29196508, 2017). "To study this further from a genomic perspective, we analyzed the correlation between FUT9 copy number and the copy number levels of known early and late genetic markers of colorectal cancer." (PMID 29196508, 2017). "Our description of this complex action of FUT9 identifies an entirely new player in colorectal cancer and adds another intriguing member to the rather short list of metabolic genes that have been shown to play a critical role in tumor biology." (PMID 29196508, 2017). "To determine the effect of FUT9 on migration of colorectal cancer cells, we performed wound‐healing assays." (PMID 29196508, 2017). "In agreement, our computational analysis showed a positive correlation between FUT9 expression and survival of colorectal cancer patients." (PMID 29196508, 2017). "However, the preferred carrier molecules of Lewisx, synthesized by FUT4 and FUT9 in colorectal cancer cells, have been scarcely studied so far." (PMID 30476078, 2019). "Additionally, the induction of complex N-glycan synthesis in MC38 cells upon FUT4 and FUT9 induction raises a possible role for these fucosyltransferases in the metabolic control of colorectal cancer cells." (PMID 30476078, 2019). "Therefore, we sought to transcriptionally activate the Fut4 and Fut9 genes in the well-known murine colorectal cancer cell line, MC38, which lacks expression of the FUT4 and FUT9 enzymes." (PMID 30476078, 2019). "The role of FUT9 in colorectal cancer appears to be rather complex." (PMID 29196508, 2017). "Overall, our findings support a dual role for FUT9 in colorectal cancer." (PMID 29196508, 2017). "Conversely, the FUT4- and FUT9-mediated synthesis of DC-SIGN and MGL-1 ligands containing the Lewisx epitope hints to potential implication of these enzymes in the induction of an immunosuppressive tumor microenvironment in colorectal cancer." (PMID 30476078, 2019). "Specifically, in colorectal cancer cells, increased levels of the fucosylated Lewisx antigen are attributed to the deregulated expression of pertinent fucosyltransferases, like fucosyltransferase 4 (FUT4) and fucosyltransferase 9 (FUT9)." (PMID 30476078, 2019). "However, the biosynthetic properties of the FUT4 and FUT9 enzymes and the potential effect of increased Lewisx expression on the glycosylation status of colorectal cancer cells have not been fully investigated yet." (PMID 30476078, 2019). "Although high expression of fucosylated epitopes has been observed in many human colorectal cancer cell lines, our MC38 wild type cells did not express any fucosylated type I or type II Lewis antigens on their cell surface and were completely devoid of Fut4 and Fut9 gene expression." (PMID 30476078, 2019).
colorectal cancer (continued). "More specifically, we demonstrate here that de novo synthesis of the fucosylated Lewisx antigen by FUT4 and FUT9 leads to potent alterations in the N-glycome of colorectal cancer cells, with a negative impact exerted on core-fucosylation and the α2-3 sialylation levels." (PMID 30476078, 2019).
adenoma (1 paper, 2017). A neoplasm arising from the epithelium. "As evident, only the knockdown of PTEN and FUT9 is predicted to transform the metabolic state of healthy cells as well as that of adenoma cells to that of colorectal tumors with high OTS scores." (PMID 29196508, 2017).
Anxiety (1 paper, 2019). Intense feelings of nervousness, tension, or panic often arise in response to interpersonal stresses. "FUT9 promotes neural development, and the knockout of FUT9 results in the development of anxiety-like behaviors in mice." (PMID 31601791, 2019).
brain cancer (1 paper, 2024). A primary or metastatic malignant neoplasm affecting the brain. "No specific glycosylation pathway was associated with this cluster, although they express the gene FUT9, which was overexpressed in brain cancers in bulk transcriptomic analysis." (PMID 38384845, 2024). "Brain cancers are characterized by a high expression of the α1-3 fucosyltransferase FUT9, which has been shown to catalyze the synthesis of the LewisX antigen in mouse models." (PMID 38384845, 2024).
colon adenoma (1 paper, 2017). An adenoma that arises from the colon. "To evaluate the effect of FUT9 knockdown (KD) and overexpression (OE) on biomass production, glucose consumption, lactate production, and oxygen consumption in the benign colon adenoma state, we (i) simulated the wild‐type metabolic state associated with colon adenoma." (PMID 29196508, 2017).
colorectal adenoma (1 paper, 2017). An adenoma that arises from the colon or rectum. "Notably, in accordance with that, we found that FUT9 expression is maintained in earlier tumors: colorectal polyps and colorectal adenoma at the levels observed in healthy colon tissue (studied in paired, matched samples), while FUT9 levels progressively decrease from the M0 to M1 stages." (PMID 29196508, 2017).
diabetic neuropathy (1 paper, 2020). A chronic, pathological complication associated with diabetes mellitus, where nerve damages are incurred due to diabetic microvascular injury involving small blood vessels that supply these nerves, resulting in peripheral and/or autonomic nerve dysfunction. "A second novel SNP for lipase, rs9377343, is an intronic variant in FUT9, a gene that showed association with diabetic neuropathy in a trans-ethnic meta-analysis." (PMID 33175840, 2020).
epilepsy (1 paper, 2024). A brain disorder characterized by episodes of abnormally increased neuronal discharge resulting in transient episodes of sensory or motor neurological dysfunction, or psychic dysfunction. "Conversely, an increase in the expression levels of SLIT and NTRK-like family, member 1 (Slitrk1), TYRO3 protein tyrosine kinase 3 (Tyro3), epilepsy, progressive myoclonic epilepsy, type 2 gene alpha (Epm2a), fucosyl-transferase 9 (Fut9), immunoglobulin superfamily, member 9B (Igsf9b) was observed." (PMID 38535448, 2024).
esophageal squamous cell carcinoma (1 paper, 2025). Esophageal squamous cell carcinoma (ESCC) is a type of esophageal carcinoma (EC) that can affect any part of the esophagus, but is usually located in the upper or middle third. "Similarly, ELF4 is up-regulated and facilitates the expression of fucosyltransferase 9 (FUT9; encoding a cancer stem-like properties affecter) in esophageal squamous cell carcinoma, thereby enhancing cancer stem-like properties and promoting tumor progression." (PMID 40083328, 2025).
ovarian carcinoma (1 paper, 2022). A malignant neoplasm originating from the surface ovarian epithelium. "α3/4-Fucosyltransferases (FUT3, FUT4 and FUT9) are active in ovarian cancer development." (PMID 36231102, 2022).